FOXN1 (forkhead box N1)
Diseases named in the same sentence as FOXN1 in open-access papers (continued):
Sharing a sentence is not in itself a finding about the gene and the disease.
Nail dystrophy (7 papers, 2013 to 2023). Onychodystrophy (nail dystrophy) refers to nail changes apart from changes of the color (nail dyschromia) and involves partial or complete disruption of the various keratinous layers of the nail plate. "FoxN1 deletion in human also results in a catastrophic T cell deficiency, congenital alopecia and nail dystrophy." (PMID 35077450, 2022). "Although the triad of congenital AU, nail dystrophy and athymia is highly indicative of FOXN1 deficient nude SCID, there are several differential diagnoses that warrant consideration." (PMID 28077132, 2017). "Nude SCID due to FOXN1 deficiency should be suspected in infants presenting with clinical and/or laboratory evidence of immunodeficiency associated with congenital AU and nail dystrophy." (PMID 28077132, 2017). "Thirty years after its original description in the mouse, this phenotype was reported in siblings from Acerno in Italy who presented with T-B+NK+ SCID, congenital alopecia totalis and nail dystrophy, and were found to have a homozygous nonsense mutation in FOXN1 (R255X)." (PMID 33257998, 2021). "Nail dystrophy has also been found in heterozygous carriers of FOXN1 mutations." (PMID 28077132, 2017). "Similar to Foxn1 null mice and rats, NuRabbits are hairless, are athymic, and exhibit nail dystrophy." (PMID 33606990, 2021). "The associated alopecia and nail dystrophy are not corrected by thymus transplantation, reflecting an intrinsic role for FOXN1 in epithelial cells at these sites." (PMID 33257998, 2021). "Of note, nail dystrophy has also been observed in heterozygous subjects carrying FOXN1 alterations." (PMID 23874334, 2013). "FOXN1 is known to be selectively expressed in the nail matrix, where the nail plate originates, thus confirming that this transcription factor is involved in the maturation process of nails and suggesting nail dystrophy as an indicative sign of heterozygosity for this molecular alteration." (PMID 23874334, 2013).
T cell deficiency (7 papers, 2018 to 2026). "The mutation in the Foxn1 “nude” gene results in two independent consequences: T cell deficiency and a hairless skin phenotype." (PMID 29637306, 2018). "The Foxn1 gene mutation leads to the development of thymus defects and T-cell deficiency." (PMID 41530841, 2026).
breast cancer (6 papers, 2012 to 2023). A primary or metastatic malignant neoplasm involving the breast. "For instance, the MCF7 and T47D hormone-receptor-positive breast cancer cell lines were implanted into female athymic Nude-FoxN1 mice." (PMID 38202341, 2023). "Next, we stained the tibia of mice injected with an admix of MDA-MB-231GFP/Luc2 human breast cancer cells plus MC3T3-E1 murine osteoblasts using antibodies for FOXN1, to show the population of injected MC3T3-E1 cells, and RUNX2 a unique marker of osteoblasts." (PMID 30813947, 2019). "In contrast with the highly aggressive MDA-MB-231 cells which develop into mammary tumors when transplanted into animals, inoculation of MCF-7 cells into 6–8 week-old female Foxn1 nu/nu Balb/c athymic nude mice without exogenously added estrogen did not form growimg tumors." (PMID 22808264, 2012).
CHARGE syndrome (6 papers, 2020 to 2022). CHARGE syndrome is a multiple congenital anomaly syndrome characterized by the variable combination of multiple anomalies, mainly Coloboma; Choanal atresia/stenosis; Cranial nerve dysfunction; Characteristic ear anomalies (known as the major 4 C's). "It is associated with several genetic and syndromic disorders including FOXN1 deficiency, 22q11.2 deletion, CHARGE Syndrome (Coloboma, Heart defects, Atresia of the nasal choanae, Retardation of growth and development, Genitourinary anomalies, and Ear anomalies), and Complete DiGeorge Syndrome." (PMID 33987750, 2021). "Other genes, implicated in thymic organogenesis include FOXN1, associated with Nude SCID syndrome, PAX1, associated with Otofaciocervical Syndrome type 2, and CHD7, one of the genes implicated in CHARGE syndrome." (PMID 32922396, 2020). "Clinical features may guide the selection of targeted genetic tests, for example cytogenetic tests such as fluorescence in situ hybridization (FISH) or comparative genomic hybridisation (CGH) where there are features of 22q11.2del, CHD7 sequencing for CHARGE syndrome, and FOXN1 for nude SCID." (PMID 33257998, 2021).
thymic atrophy (6 papers, 2014 to 2025). "FOXN1 is a master transcription regulator for the growth and differentiation of TECs, and declined FOXN1 gene expression contributes to age-related thymic atrophy." (PMID 33808998, 2021).
lung carcinoma (5 papers, 2021 to 2025). "This suggests that we should contemplate the pivotal function and the clinicopathological traits of FOXN1 in the context of lung cancer." (PMID 39628682, 2024). "Although there is a growing body of research on FOXN1, reports on its role in lung cancer are infrequent, and the specific mechanisms by which FOXN1 functions in LUSC remain largely unknown." (PMID 39628682, 2024). "Animals: female athymic nude Foxn1 mice xenografted with human lung cancer cell line A549." (PMID 34577056, 2021). "We focused on the expression of FOXN1 in LUSC and did not extend our analysis to other subtypes of lung cancer." (PMID 39628682, 2024).
primary immunodeficiency (5 papers, 2017 to 2024). "We have therefore identified the cause for a primary immunodeficiency disease and determined the mechanism by which this FOXN1 gain-of-function mutant mediates its dominant negative effect." (PMID 34860543, 2021). "Finally, we substantiate GRN model predictions by characterizing molecular and cellular impact of a perturbation targeting Foxn1, which encodes a forkhead box DNA binding TF, resulting in developmental defects that underly primary immunodeficiency." (PMID 35075189, 2022). "Moreover, we provide a molecular explanation how a previously unidentified FOXN1 mutant dominantly interferes with the dynamic formation of transcriptional hubs ultimately causing a form of a primary immunodeficiency." (PMID 34860543, 2021). "The SGM rabbits we produced in this study can be used for modeling corresponding human primary immunodeficiency diseases: FOXN1 (OMIM# 600838), IL2RG (OMIM# 300400), RAG2 (OMIM# 601457), and PRKDC (OMIM# 600899)." (PMID 28939872, 2017). "For example, several immunodeficient rabbit lines have been produced by knocking out of genes such as Il2rg, Foxn1, and Rag2; these animals are expected to make valuable contributions to regenerative medicine, cancer and primary immunodeficiency, as comprehensively reviewed elsewhere." (PMID 33584832, 2021). "Targeted genetic testing with the Invitae primary immunodeficiency panel revealed two heterozygous VUS, that is, in DOCK8 (C.277G>T, p.Val93Leu) and FOXN1 (c.1205del, p.Pro402Leufs*148)." (PMID 39008056, 2024).
thymoma (5 papers, 2022 to 2024). A neoplasm arising from the epithelial cells of the thymus. "Therefore, it is not surprising that transgenic mouse models expressing mutated Gtf2i under the promoter of Foxn1 develop thymomas with cortical features instead of medullary features." (PMID 37671056, 2023). "This suggests that FOXN1 serves as a sensitive and specific marker for differentiating thymic carcinoma from thymoma." (PMID 39628682, 2024). "FOXN1 promotes the proliferation of thymic epithelial progenitor cells and mTECs in the normal thymus and in thymoma cells." (PMID 38473304, 2024). "In line with this peculiarity of TETs, induced WNT4 expression in thymoma-derived pTECs was positively correlated with the expression of FOXN1." (PMID 35965500, 2022). "The FOXN1 protein is expressed in most thymomas but partially lost in TCs." (PMID 38473304, 2024).
Thymic aplasia (4 papers, 2020 to 2023). "Autosomal recessive mutations in the Forkhead Box N1 (FOXN1) transcription factor cause a T−B+NK+ SCID phenotype due to a thymic aplasia as well as alopecia universalis and nail plate dystrophy (OMIM #601705)." (PMID 32431714, 2020). "Mutations in the Foxn1 gene result in thymic aplasia, lack of T cells, and no immunological rejection." (PMID 37007087, 2023).
Cachexia (3 papers, 2016 to 2019). Severe weight loss, wasting of muscle, loss of appetite, and general debility related to a chronic disease. "Indeed, in animal studies, the administration of Lactobacillus reuteri, which modulates the transcriptional factor Forkhead Box N1 (FoxN1), was able to prevent cachexia in murine models of cancer." (PMID 31443594, 2019). "In conclusion, symbiotic bacteria may serve to stimulate FoxN1 and thymic functions that regulate inflammation, offering possible alternatives for cachexia prevention and novel insights into roles for microbiota in mammalian ontogeny and phylogeny." (PMID 26933816, 2016).
colon cancer (3 papers, 2021 to 2025). "Animals: female athymic nude Foxn1 mice xenografted with human colon cancer cell line SW480." (PMID 34577056, 2021).
glioblastoma (3 papers, 2008 to 2022). The most malignant astrocytic tumor (WHO grade IV). "The authors showed that LDM temozolomide (1.77 mg/kg/day) was effective, from the beginning of the treatment, in hampering the growth of an orthotopic human U87MG-luc2 glioblastoma xenograft, implanted intracranially in Foxn1 nude mice." (PMID 36362482, 2022).
melanoma (3 papers, 2013 to 2024). A malignant, usually aggressive tumor composed of atypical, neoplastic melanocytes. "A possible reason for this upregulation of FOXN1 is that melanoma patients in the high-risk group tend to have worse tumor progression and often develop skin ulceration." (PMID 36875110, 2023). "We found that H2-Aaflox/flox;Foxn1-cre mice efficiently inhibited B16F10 melanoma growth." (PMID 39470607, 2024). "In the next step we investigated whether intratumorally administered NVP-LDE225 is able to inhibit the growth of human melanoma cells in athymic Nude-Foxn1 nu/nu mice." (PMID 23935925, 2013). "To address whether lack of CD4 T cells also contributes to melanoma growth restriction in H2-Aacit/cit mice, we generated H2-Aaflox/flox;Foxn1-cre mice, in which H2-Aa was deleted specifically in thymic epithelial cells, thus blocking CD4 T cell development." (PMID 39470607, 2024).
Obesity (3 papers, 2020 to 2023). Accumulation of substantial excess body fat. "Our recent data showed that Foxn1 inefficiency in mice (Foxn1+/− mice) results in a decrease in susceptibility to diet-induced obesity." (PMID 35008683, 2021). "Our recent data based on a mouse model (Foxn1+/− and Foxn1−/− mice) also showed that Foxn1 controls adipogenic signaling that regulates skin homeostasis and wound healing and affects susceptibility to diet-induced obesity." (PMID 37893027, 2023). "Our recent data demonstrated that Foxn1 may regulate susceptibility to diet-induced obesity." (PMID 33255750, 2020). "We also demonstrated that a decrease in Foxn1 activity is related to a resistance to diet-induced obesity in Foxn1+/− mice, and that Foxn1 regulates dWAT capacity since Foxn1+/− mice showed an altered expression of adipogenic genes in non-injured and post-injured skin." (PMID 35008683, 2021).
acute lymphoblastic leukemia (2 papers, 2017 to 2024). Leukemia with an acute onset, characterized by the presence of lymphoblasts in the bone marrow and the peripheral blood. "To evaluate the effect of Foxn1 deletion on the engraftment capacity of hematological cells, we compared the engraftment of a human B cell acute lymphoblastic leukemia (B-ALL) cell line, Nalm6, in NDG, NOG, NSI, and NSIN mice." (PMID 28798321, 2017).
autoimmune disease (2 papers, 2010 to 2026). A disorder resulting from loss of function or tissue destruction of an organ or multiple organs, arising from humoral or cellular immune responses of the individual to their own tissue constituents. "The extent of autoimmune disease in Aire KO mice is dependent on the genetic background, with very mild disease observed on the mixed 129xB6 background (which incidentally, is the same background as the Adam17/Foxn1 mice used in our studies)." (PMID 20976004, 2010). "Adam17/Foxn1 mice do not display any overt phenotypes that would indicate autoimmune disease, which is consistent with the normal thymic phenotype and production of mature T cells observed in two-to-three-month-old Aire KO mice." (PMID 20976004, 2010).
esophageal cancer (2 papers, 2023 to 2025). A primary or metastatic malignant neoplasm involving the esophagus. "Esophageal cancer patients with high expression of FOXN1, GRHL3, and HES2, stomach cancer patients with high expression of ONECUT2, thyroid cancer patients with high expression of PAX8, and uterine cancer patients that expressed elevated levels of MECOM had decreased survival." (PMID 37627195, 2023). "This is further supported by previous findings wherein Evofos, in combination with radiotherapy (X-rays), did not induce normal tissue toxicity in the Nu-Foxn1-nu (NU/NU) mouse model for esophageal cancer." (PMID 40563638, 2025).
graft versus host disease (2 papers, 2021 to 2022). An immune system disorder that occurs after allogeneic hematopoietic stem cell transplant and is a reaction of donor immune cells against host tissues. "The malfunction or even impairment of thymus development is linked with several diseases like the DiGeorge Syndrome (DGS), Foxn1 deficiency, graft-versus-host disease (GVHD), HIV infection, or autoimmune diseases." (PMID 35844535, 2022).
lymph node metastasis (2 papers, 2023 to 2024). "Our investigation revealed that several significant factors—namely, distant metastasis, lymph node metastasis, tumor grading, and stage—were correlated with FOXN1 expression in an independent manner." (PMID 39628682, 2024). "Comparative analysis between different groups revealed that FOXN1 expression is correlated with distant metastasis, lymph node metastasis, grading, and stage of LUSC." (PMID 39628682, 2024).
osteosarcoma (2 papers, 2018 to 2023). A usually aggressive malignant bone-forming mesenchymal neoplasm, predominantly affecting adolescents and young adults. "In vitro studies on U2OS osteosarcoma cells transfected with Foxn1 demonstrate increased PLC-δ1 at mRNA and protein levels, strongly suggesting regulation of this gene by Foxn1 in the skin." (PMID 29973508, 2018).
sarcopenia (2 papers, 2016 to 2021). Progressive decline in muscle mass due to aging which results in decreased functional capacity of muscles. "have shown that the administration of Lactobacillus reuteri in mouse models of cancer could inhibit the development of sarcopenia and increase in muscle weight and fiber size, through an up-regulation of the transcriptional factor Forkhead Box N1 (FoxN1)." (PMID 34326845, 2021). "Interestingly, mice with a defective FoxN1 gene (athymic nude) fail to inhibit sarcopenia after L. reuteri therapy, indicating a FoxN1-mediated mechanism." (PMID 26933816, 2016).
allergic asthma (1 paper, 2015). A asthma with a basis in a pathological type I hypersensitivity reaction. "In our data, TGFBI and FOXN1 do not correlate with each other in normal tissue, while they present negative correlation in Allergic asthma (−0.76); meanwhile, the positive correlation of TGFBI and FZD8 in normal tissue is reversed to be negative in T2D (from 0.63 to −0.86)." (PMID 26450611, 2015).
asthma (1 paper, 2015). "According to our data, Wnt pathway involves three common DCGs including FZD8, FOXN1 and TLE2, among which only FZD8 was reported to participate in the pathogenesis of Asthma, and display abnormal expression in Chronic kidney disease." (PMID 26450611, 2015). "There are no literatures on the roles of FOXN1 and TLE2 in Asthma, T2D and Chronic kidney disease in the public domain." (PMID 26450611, 2015).
atherosclerosis (1 paper, 2024). A disease characterized by the build-up of fatty material and calcium deposition in the arterial wall resulting in partial or complete occlusion of the arterial lumen. "Another ubiquitously expressed molecule, which may be the potential target both in thymus involution and atherosclerosis, is forkhead box protein N1 (Foxn1)." (PMID 39061983, 2024). "There is also a hypothesis that low-density lipoproteins cholesterol, a potent factor of atherosclerosis, may reduce an important thymic regulatory factor, Foxn1, leading to decline of the thymic function." (PMID 39061983, 2024). "Thus, one should be cautions considering the influence on Foxn1 during atherosclerosis treatment." (PMID 39061983, 2024).
Atrophy (1 paper, 2020). Any weakening or degeneration, especially through lack of use. "Since the advent of cell-type specific conditional gene knock-out (cKO) models, compelling evidence show that age-related thymic atrophy is tightly associated with postnatal TEC homeostasis, regulated by TEC autonomous transcription factors (TFs), such as Forkhead box N1 (FOXN1)." (PMID 31988649, 2020). "Additionally, use of FOXN1 reporter mice have enabled further elucidation of the timeline and kinetics of thymic atrophy with age." (PMID 31988649, 2020).
brain tumors (1 paper, 2015). "In a further step, the virus injection site in athymic Foxn1 nu/nu mice without brain tumors was analyzed by immunohistochemical stainings of brain sections 1 and 3 days post infection (dpi)." (PMID 26149494, 2015).
cyst (1 paper, 2017). A sac-like closed membranous structure that may be empty or contain fluid or amorphous material. "The aberrant surface phenotype of the thymic epithelium is magnified in Foxn1+/−;Foxn1:Noggin mice, in which the thymus consists of a large cyst; keratin 5-positive epithelial cells occupy a basal location and only few, if any, haematopoietic cells are present." (PMID 28819138, 2017).
embryonic carcinoma (1 paper, 2016). "In embryonic carcinoma cells treated with BMP-2 to adopt an epithelial phenotype, miR-518b was shown to directly target FOXN1—a transcription factor critical for thymus development and epithelial differentiation." (PMID 27529341, 2016).
Failure to thrive (1 paper, 2021). Failure to thrive (FTT) refers to a child whose physical growth is substantially below the norm. "FOXN1 mutation was identified through NGS in the 2 siblings presenting in the first month of life with a CID phenotype characterized by pneumonia, diarrhea, and failure to thrive." (PMID 33464451, 2021).
glioma (1 paper, 2024). A benign or malignant brain and spinal cord tumor that arises from glial cells (astrocytes, oligodendrocytes, ependymal cells). "Both glioma cell lines (U87MG and its STAT3 knockout variant U87MG-STAT3KO) were next implanted into the Foxn1-nude mice and for 28 days the tumor growth was monitored with simultaneous administration (from 15th day after implantation) of TMZ at 0.9 mg/kg concentration." (PMID 38654280, 2024).
Hypercholesterolemia (1 paper, 2013). An increased concentration of cholesterol in the blood. "Among the DEGs that were down-regulated in the hypertension plus hypercholesterolemia group were FOXN1, TNFRSF11B, and GAPDHS." (PMID 23874591, 2013). "Among the DEGs that were down-regulated in common, between the hypertension only, and hypercholesterolemia plus sham groups (both vs. sham controls) were FOXN1, Ribosomal protein S3-like (LOC100354966) and ADAMTS17 (ADAM metallopeptidase with thrombospondin type 1 motif, 17)." (PMID 23874591, 2013).
Hypertension (1 paper, 2013). The presence of chronic increased pressure in the systemic arterial system. "Among the down-regulated DEGs in the MCA of the hypertension only group were FOXN1, NSRP1 and THUMPD3." (PMID 23874591, 2013). "Among the highly down-regulated genes in the MCA of the hypertension only group were FOXN1, ribosomal protein S3a-like and ADAMTS17." (PMID 23874591, 2013).